GINS2 (GINS complex subunit 2)
Diseases named in the same sentence as GINS2 in open-access papers (continued):
Sharing a sentence is not in itself a finding about the gene and the disease.
tumor (continued). "With the gradual increase of the pathological stages of ACC, HNSC, KIRC, KIRP, LUAD, and TGCT tumours, the expression of GINS2 also increased accordingly." (PMID 36466552, 2022). "After equilibrating the effect of tumor purity, the results revealed that the GINS2 level showed positive correlation with most markers of activated T cells in HCC." (PMID 35069907, 2022). "The number of neoantigens in each tumour sample was counted, and the relationship between GINS2 expression and the number of these neoantigens was analyzed." (PMID 36466552, 2022). "In KICH, KIRC, HNSC, and other tumours, the expression of GINS2 is positively correlated with the gene expression in immune checkpoints." (PMID 36466552, 2022). "The correlation between TMB and GINS2 expression in various tumours was statistically analyzed by the Spearman rank correlation coefficient." (PMID 36466552, 2022). "After equilibrating the effect of tumor purity, transcriptional levels of GINS2 were positively related with most marker gene sets of CD8+ T cells, T cells (general) and Th1 cells in HCC." (PMID 35069907, 2022). "On the contrary, the high expression of GINS2 is associated with the protective factor in THCA and THYM tumours." (PMID 36466552, 2022). "In DLBC, GBM, TGCT, THYM, and other tumours, the expression of GINS2 is negatively correlated with gene expression in immune checkpoints." (PMID 36466552, 2022). "Firstly, the correlation of GINS2 expression in 33 tumours with OS, DSS, DFI, and PFI was studied using single-factor Cox analysis based on TCGA database." (PMID 36466552, 2022). "Cell cycle and DNA replication were two main processes that enriched in tumor cells overexpressed GINS2 gene (NES = 1.848, P = 0.007; and NES = 1.907, P = 0.005, respectively)." (PMID 35069907, 2022). "GINS2 expression was undoubtedly higher in HCC tumor samples than in normal specimens and showed a pan-cancer overexpression signature." (PMID 35069907, 2022). "The results confirmed that GINS2 presentation shows a significantly positive correlation with methyltransferase expression in most tumours, especially in BLCA, KICH, KIRP, LAML, LGG, LIHC, and TGCT." (PMID 36466552, 2022). "In conclusion, our study suggests that GINS2 is a potential prognostic biomarker for HCC patients and is associated with the abundance of infiltrating immune cells in tumor tissues." (PMID 35069907, 2022). "By contrast, GINS2 gene was significantly overexpressed in tumor samples of the GSE77314, GSE45436, GSE36376, GSE25097, GSE14520 and TCGA datasets (all P < 0.01)." (PMID 35069907, 2022). "Tumorigenesis assays showed that the volume, size and weight of tumors in the shGINS2 group were significantly decreased compared to those in the control group, demonstrating that GINS2 knockdown inhibited tumor proliferation and growth in vivo." (PMID 33391406, 2021). "GINS2 expression in OC tumor tissues was upregulated by approximately 8-fold compared to that in normal tissues." (PMID 34288816, 2021). "Further functional experiments confirmed that the tumor suppressive effect of miR-502-5p on OC was realized through targeted GINS2 inhibition." (PMID 34288816, 2021). "Our results indicated that the expression of GINS2 was significantly down-regulated in tumour tissues, and the NSCLC cell lines A549 and H460." (PMID 32181475, 2020). "Subsequently, the effects of GINS2 interference on the cell viability, cell apoptosis, cell cycle, and tumor growth in nude mice were analyzed." (PMID 32626512, 2020). "Taken together with our in vivo mediator experiments (Ly6G neutrophil depletion and PD-L1 blockade), we interpret the T-cell phenotype as indirect—arising via PD-L1+ tumor-associated neutrophils—rather than direct transcriptional control by GINS2." (PMID 41322418, 2025).
tumor (continued). "Our in-vivo approach intentionally employed a reductionist human OSCC xenograft configuration with adoptive human T cells and neutrophils to isolate the mechanistic sequence whereby tumor-intrinsic GINS2 promotes TAN recruitment, induces PD-L1 on TANs, and suppresses CD8+ T-cell function." (PMID 41322418, 2025). "This duality provides the conceptual basis for our hypothesis that tumor-intrinsic GINS2 not only drives proliferation but also recruits and polarizes TANs toward immunosuppressive states that blunt CD8+ T-cell function in OSCC." (PMID 41322418, 2025). "Targeting GINS2 via shRNA knockdown combined with T cells and neutrophils showed anti-tumor activity, but the addition of anti-PD-L1 blockade yielded the most profound tumor suppression, accompanied by reduced Ki67 expression." (PMID 41322418, 2025). "Significantly, GINS2 actively shapes an immunosuppressive tumor microenvironment by correlating with T cell exhaustion markers and, crucially, by promoting the recruitment of pro-tumorigenic neutrophils that express high levels of PD-L1, thereby inhibiting anti-tumor T cell responses." (PMID 41322418, 2025). "However, the transplanted tumors formed by LN229-GINS2 KO cells were smaller than those in the control group, suggesting that depleting GINS2 mitigated the tumor-forming ability of LN229 cells." (PMID 38467631, 2024). "Therefore, this study is aimed at investigating the prognostic value and immune-related role of GINS2 in human tumours and providing a comprehensive understanding of its carcinogenic mechanism in pan-cancer." (PMID 36466552, 2022). "Whether GINS2 can play a role in the pathogenesis of different tumours through some of the exact molecular mechanisms still needs further investigation." (PMID 36466552, 2022). "Previous reports suggested that the subtype derived from stromal contents is a strong indicator of tumor aggressiveness and poor prognosis, which was consistent with the inherent characteristics of stromal-derived GINS2 subtype." (PMID 36345721, 2022). "In addition, some reports have revealed that GINS2 overexpression bring unfavorable outcomes in different tumor types, such as non-small-cell lung cancer (NSCLC), breast and cervical cancer 14-16." (PMID 35069907, 2022). "GINS2 plays a potential carcinogenic role in various human tumours through mRNA and protein levels." (PMID 36466552, 2022). "Finally, the changes in the GINS2 gene in 33 tumours and 10,953 patients were studied based on the cBioPortal network platform." (PMID 36466552, 2022). "Moreover, the transcriptional data from the GEPIA database also confirmed the overexpression of GINS2 in tumor samples (red)." (PMID 35069907, 2022). "We performed an experiment to explore the effect of GINS2 on tumor progression in vivo." (PMID 33391406, 2021). "Additionally, the increased expression of GINS2 in tumor tissues observed in the NSCLC cohort supported the crucial role of GINS2 in NSCLC development." (PMID 33391406, 2021). "Finally, PANC-1 cells with GINS2 knockdown were subcutaneously injected into nude mice to evaluate the effects of GINS2 on tumor growth in vivo." (PMID 32626512, 2020). "Additionally, the effects of GINS2 interference on the cell viability, cell apoptosis, cell cycle, and tumor growth in nude mice were analyzed." (PMID 32626512, 2020). "The results of an established cancer xenograft model revealed that nude mice transplanted with cells expressing negative control (NC) exhibited larger and heavier tumors, while volume and weight of tumor were remarkably reduced in ones transplanted with cells expressing GINS2 siRNA." (PMID 32626512, 2020). "In addition, we discovered for the first time that GINS2 regulated drug sensitivity in tumor cells." (PMID 38467631, 2024). "Furthermore, GINS2 knockdown effectively inhibited the growth of a xenograft tumor in vivo." (PMID 36873736, 2023). "Therefore, GINS2 is an important factor affecting the prognosis of tumours." (PMID 36466552, 2022).
tumor (continued). "Therefore, the expression of GINS2 can promote the progression of these tumours." (PMID 36466552, 2022). "Therefore, GINS2 can regulate the expression of some related immune checkpoint genes in some tumours, to play an essential role in regulating tumour-resistant mode (∗ represents correlation P < 0.05, ∗∗ represents correlation P < 0.01, and ∗∗∗ represents correlation P < 0.001)." (PMID 36466552, 2022). "Silencing GINS2 robustly inhibited OSCC cell proliferation, colony formation, migration, and invasion, while also significantly curtailing xenograft tumor growth in nude mice." (PMID 41322418, 2025). "GINS2 acts as a key oncogenic driver in OSCC, promoting tumor progression and facilitating immune evasion." (PMID 41322418, 2025). "GINS2 knockdown sensitized OSCC models to anti-PD-L1 therapy, reducing tumor growth and Ki67 expression, particularly when combined with T cells and neutrophils." (PMID 41322418, 2025). "Relevant research reports pointed out that high expression of GINS2 had a clear connection with the occurrence and development of many malignant tumors, and it could also play an effective role in the tumorigenesis stage by regulating tumor cell apoptosis, signaling pathways, and the cell cycle." (PMID 36873736, 2023). "In recent years, more and more reports have shown that GINS complex subunit 2 (GINS2) plays an important role in the occurrence and progression of tumours." (PMID 36466552, 2022). "Subtypes with rich stromal components (e.g. GINS2 and GINS4) in human CRC samples were inclined to transform into subtypes with high tumor purity (e.g. GINS1 and GINS3) in corresponding PDX derivatives." (PMID 36345721, 2022). "Therefore, GINS2 may play a crucial role in cancer prognosis and tumour immunity." (PMID 36466552, 2022). "We found that CYP7A1, GINS2, and PDLIM3 were significantly up-regulated, and MYC, MAMDC4, ADAMTS1, THBS1, and RASD1 were significantly down-regulated in HCC tumor samples compared to normal samples." (PMID 34777484, 2021). "We found that CYP7A1, GINS2, and PDLIM3 were significantly up-regulated, and MYC, MAMDC4, ADAMTS1, THBS1, and RASD1 were significantly down-regulated in HCC tumor samples compared with normal samples using the TCGA dataset." (PMID 34777484, 2021). "We used qRT‐PCR to detect expression of GINS2, miR‐515‐5p and EMT markers in operated tumour tissues." (PMID 32596993, 2020). "Comparing polymerase components across thirty-seven tumor types revealed a common subset with elevated transcriptional pattern typified by POLE2 and POLQ that included EXO1, MCM10, GINS2, CDT1, ORC6L, and BLM." (PMID 31857847, 2019). "Consistent with the ONCOMINE analysis, all four GINS genes were up-regulated in tumor samples of HCC from TCGA database with 6.382, 3.789, 2.442, and 2.770-fold elevation for GINS1, GINS2, GINS3, and GINS4 mRNA expressions, respectively (P<0.001 for all)." (PMID 30413605, 2018). "Immunofluorescence of patient OSCC sections identified CD8+ tumor-infiltrating lymphocytes (TILs); epithelial tumor cells (GINS2+) showed no CD8 signal." (PMID 41322418, 2025). "The strong positive correlation between tumor GINS2 levels and neutrophil PD-L1 MFI suggests that GINS2 not only recruits neutrophils but also shapes their immunosuppressive potential." (PMID 41322418, 2025). "As GINS2, GINS4, which were also involved in the DNA replication process, previous studies had reported that they were abnormally expressed in many tumor tissues including KIRC, affecting tumor development." (PMID 37642814, 2024). "Although the number of tumor cells that expressed GINS2 was higher than normal cells, the results were not statistically significant, because of the lower differences in the mean expression of the hub gene between the two cell populations." (PMID 37945594, 2023). "The regulation of GINS2 by the downstream signaling pathways in tumor cells is not yet fully understood." (PMID 36873736, 2023).
tumor (continued). "GINS2 was positive correlated with tumor purity (r = 0.26, p = 3.78e-05), and negative correlated with the levels of tumor-infiltrating macrophages (r = −0.137, p = 3.57e-02)." (PMID 36092720, 2022). "The IHC analysis showed that the protein expression of GINS2 in tumor samples was significantly higher than those in matched nontumor tissues." (PMID 35069907, 2022). "Based on the TIMER database, the scores of six kinds of infiltrating immune cells related to 33 tumours (B cells, CD4+ T cells, CD8+ T cells, neutrophils, macrophages, and dendritic cells) were calculated, and the correlation of GINS2 expression with these immune cells was analyzed." (PMID 36466552, 2022). "Finally, the correlation between GINS2 and CAF abundance in most tumours was studied, and an enrichment analysis of GINS2 and its related proteins was also carried out." (PMID 36466552, 2022). "In addition to detecting gene expression, we found that GINS2 knockdown increased STAT1 and STAT2 protein expression and inhibited tumor migration and proliferation, which was consistent with a previous study." (PMID 33391406, 2021). "Meanwhile, a negative correlation between miR-502-5p expression and GINS2 expression was observed in OC tumor tissues." (PMID 34288816, 2021). "MP-HX downregulated the expression of genes that could promote anti-apoptotic effect, cell cycle progression, tumor development and progression, which include BIRC5, CCNA2, CCNB1, CCNB2, CCNE2, CDK1/2/6, GINS2, HELLS, MCM2/10 PLK1, RRM2 and SKP2." (PMID 30042885, 2018). "Apart from the immune activation represented by GINS5, GINS1/2/3 displayed sparse infiltration of cells that promote immune activity, but unlike GINS2, GINS1/3 were also characterized by rare immunosuppressive cells, consistent with their high tumor purity." (PMID 36345721, 2022).
cancer (23 papers, 2013 to 2025). A tumor composed of atypical neoplastic, often pleomorphic cells that invade other tissues. "Among the five with the lowest context++ scores, GINS2 was once reported to be a cancer driver in OC and was associated with worse prognosis in OC patients." (PMID 34288816, 2021). "This aligns with findings in other cancer types where GINS2 upregulation is frequently associated with aggressive behavior and poor outcomes, reinforcing the idea that dysregulation of fundamental DNA replication components is a common feature contributing to malignancy." (PMID 41322418, 2025). "In addition, GINS2 is abnormally expressed in various cancers, which is significantly associated with MMR, MSI, DNA methylation, and TMB." (PMID 36466552, 2022). "Recognizing the crucial role of the TME in cancer progression, we investigated the relationship between GINS2 expression and immune infiltration in OSCC using TCGA data analyzed via TIMER2.0." (PMID 41322418, 2025). "Mechanistically, GINS2 regulates cancer-cell proliferation via the phosphatase PTP4A1 (PRL-1), establishing a direct GINS2→PTP4A1 link." (PMID 41322418, 2025). "Functionally, our in vitro and in vivo experiments unequivocally establish GINS2’s role in promoting core cancer hallmarks in OSCC." (PMID 41322418, 2025). "GINS2, a subunit of DNA helicase, contributes to maintaining genomic stability and is highly expressed in various cancers, promoting their development." (PMID 38467631, 2024). "IPA revealed that multiple signaling pathways related to cancer development and apoptosis, such as the mTOR and IL-8 signaling pathways, were inhibited by GINS2." (PMID 36873736, 2023). "To examine the potential mechanism by which GINS2 regulated the progression of OS, we performed microarray analysis to investigate the differences in cancer-related genes between ordinary OS cells and GINS2-depleted cells." (PMID 36873736, 2023). "GINS2 was overexpressed in multiple tumors and reported to be involved in tumorigenesis in several types of cancers including breast cancer, leukemia, and lung cancer." (PMID 36873736, 2023). "In this study, we first showed that GINS2 was an oncogene and highly correlated with cancer progression as well as patient survival prognosis." (PMID 36873736, 2023). "We performed a relatively comprehensive bioinformatic analysis on the clinical prognosis and immunity of GINS2 in pan-cancer." (PMID 36466552, 2022). "At the same time, GINS2 is related to immune neoantigens and the expression profiles of immune checkpoint genes in pan-cancer." (PMID 36466552, 2022). "This study shows that GINS2 is related to the prognosis of cancer patients and the immune infiltration of different cancers." (PMID 36466552, 2022). "The immune infiltration analysis showed that the expression of GINS2 is correlated with the immune infiltration level in different cancers." (PMID 36466552, 2022). "The results showed that GINS2 mRNA and protein expression were highly expressed in cancer tissue, indicating that GINS2 was related to the occurrence and development of NSCLC." (PMID 33391406, 2021). "Aberrant expression of the GINS complex subunit 2 (GINS2) gene and miR-502-5p has been associated with cancer progression." (PMID 34288816, 2021). "To further explore the effects of GINS2 knockdown, we established cancer xenograft model in nude mouse by subcutaneous injection of NC and siGINS2 PANC-1 cells, respectively." (PMID 32626512, 2020). "Therefore, we must make more efforts to explore the effects of GINS2 in cancer and the value of GINS2 as a potential target in anticancer therapy." (PMID 36466552, 2022). "The clinical significance of GINS2 in pan-cancer was studied." (PMID 36466552, 2022). "Therefore, this study provides a relatively comprehensive content of pan-cancer analysis and thoroughly analyzes the role of GINS2 in cancer." (PMID 36466552, 2022). "Whether GINS2 genes are different in different pathological stages of other cancers has also been studied." (PMID 36466552, 2022).